SPOP (speckle type BTB/POZ protein)
Diseases named in the same sentence as SPOP in open-access papers (continued):
Sharing a sentence is not in itself a finding about the gene and the disease.
tumor (continued). "SPOP is classified as a tumor suppressor based on extensive studies, including those on cell proliferation, migration, and invasion." (PMID 39540935, 2024). "The G3BP1-SPOP bound ubiquitin activates AR signalling and upregulates G3BP1 transcription, leading to overexpression of G3BP1 in PCa tumour cells and further inhabitation of the tumour suppressor SPOP." (PMID 37749167, 2024). "In this work, we demonstrate that BCLAF1 competitively inhibits SPOP-mediated ubiquitination and degradation of PD-L1 by interacting with SPOP to maintain PD-L1 expression, ultimately promoting immune evasion and tumor progression of HCC." (PMID 38340178, 2024). "Although much knowledge of SPOP in regulating tumor stemness has been gained, studies of SPOPL in controlling stemness are limited." (PMID 36769824, 2023). "The SPOP protein is involved in the ubiquitination and consequent proteasomal degradation of target proteins; in PC, SPOP acts as a tumor suppressor by targeting several proteins, including AR, SRC3, and BRD4." (PMID 37894312, 2023). "SPOP exhibits a dual role, both as a tumor promoter and a tumor suppressor, although the research about its specific mechanism is still limited." (PMID 37941785, 2023). "Recently, SPOP was found to increase the movement of PD-1 away from PD-L1 in spatial localization, and enhanced tumor metastasis in cervical cancer." (PMID 36733484, 2023). "We found that miR-410 expression depends upon the tumor subtype, with those with ERG fusion, ETV1 fusion and SPOP mutations having a lower miR-410 expression as compared to other subtypes." (PMID 38201476, 2023). "Collectively, all of these indicated that SPOP has a tumor-promoting effect in HCC, prompting us to explore its impact further." (PMID 37941785, 2023). "Meanwhile, SPOP protein expression was amplified in tumor tissues of GBM patients, and in T98G cells compared with normal tissues and HEB cells, respectively." (PMID 37382594, 2023). "Injection of miR-873-5p agomir + oe-NC-treated T98G cells into the nude mice decreased tumor volume and weight, while miR-873-5p agomir + oe-SPOP led to opposite results." (PMID 37382594, 2023). "Conversely, the suppressed ZNFs in GC such as SPOP can impede GC progression, and in vitro tests suggested that overexpressed SPOP can block the invasion and colony formation of tumor cells by suppressing the Hh/GLI2 signaling pathway." (PMID 37174714, 2023). "The result of relationship between SPOP expression and clinicopathological parameters showed that SPOP expression was positively correlated with tumor stage." (PMID 37941785, 2023). "SPOP mutations disrupt SPOP-mediated destruction of Nanog and have been shown to promote PCSC proliferation and tumor progression." (PMID 37834336, 2023). "Previous literature has reported that HIF1α can transcriptionally activate the expression of SPOP, which has tumor-promoting effects in several types of cancer." (PMID 37382594, 2023). "Based on these findings, we utilized control and SPOP-deleted OCI-Ly7 cells infected with shCtrl or shTFEB to generate the subcutaneous tumor models." (PMID 35773729, 2022). "Given that SPOP/CHAF1A axis modulates the DLBCL tumor autophagy, we further detected the level of autophagy in DLBCL cells." (PMID 35773729, 2022). "Considering the tissue and cellular context dependent role of SPOP in tumorigenesis, here we will mainly focus on uncovering the tumor suppressor role of SPOP in PCa." (PMID 35194188, 2022). "SPOP exerts its tumor suppressor roles mainly by promoting the degradation of its oncogenic substrates, such as AR, ERG, BRD4, and Nanog6,8,9." (PMID 35233061, 2022). "To further determine the tumour-promoting effect of SPOP on cell proliferation, we measured the expression levels of SPOP in various CC cell lines." (PMID 36042498, 2022). "Taken together, SPOP/CHAF1A axis restricts tumor autophagy in a TFEB-dependent manner, and targeting TFEB-mediated signaling represents a useful strategy for SPOP-deficient DLBCL." (PMID 35773729, 2022).
tumor (continued). "Our experimental results revealed that CRCSCs-exos upregulated miR-17-5p, which targeted SPOP to promote growth and inhibit anti-tumor immunity in CRC cells through promoting PD-L1." (PMID 35461336, 2022). "Our group previously identified the presence of 2 immediately adjacent, but distinct, tumor foci found to have ERG rearrangement and F133V SPOP mutation." (PMID 35050902, 2022). "In conclusion, we demonstrated that the elevation of CRCSCs-exosomal miR-17-5p inhibits SPOP to facilitate the growth and restrain the anti-tumor immunity in CRC cells via promoting PD-L1." (PMID 35461336, 2022). "Recently, a study suggested that miRNA-17-5p can target SPOP and that upregulation of miRNA-17-5p can downregulate SPOP to promote proliferation and inhibit anti-tumor immunity in CRC through the overexpression of PD-L1." (PMID 36360288, 2022). "Down-regulated or DLBCL-associated SPOP mutations contribute to CHAF1A accumulations, thereby enhancing tumor autophagy of DLBCL in a TFEB-dependent manner." (PMID 35773729, 2022). "The results demonstrate that silencing SPOP indeed promoted tumor growth with increased tumor volume and size." (PMID 36115849, 2022). "Specifically, we found that the GILncSig was significantly linked to the tumor mutation phenotype and to PTEN, CDK12, SPOP, and TMPRSS2 expression in PCa, all of which are vital signs of genomic instability." (PMID 35860569, 2022). "Compared to the adjacent normal tissues (n = 21), tumor tissues (n = 314) showed significant lower SPOP, but higher ASCT2 levels." (PMID 35641493, 2022). "Upregulated CRCSC-exosomal miR-17-5p inhibits SPOP to promote tumor cell growth and dampen anti-tumor immunity in CRC through promoting PD-L1." (PMID 35461336, 2022). "Deficient SPOP contributes to accumulated CHAF1A proteins, thereby sustaining tumor autophagy via induction of TFEB." (PMID 35773729, 2022). "Serving as E3 ubiquitin ligases of Brg1 and AR, the tumor suppressors FBW7 and SPOP, respectively, are frequently mutated in PCa7,28,36,37." (PMID 35233061, 2022). "In the WES samples, we detected somatic mutations in known PCa genes, including KMT2D, MTOR, SPOP, and PIK3R1, indicating tumor content in tissues assessed by single-cell analysis." (PMID 35013146, 2022). "Due to the diversity of regulatory pathways and the variety of tumor types involved, SPOP has recently received increasing attention." (PMID 36119488, 2022). "If the substrates that bind to SPOP have tumor-suppressor roles, SPOP overexpression can play a tumor promoting role." (PMID 36474188, 2022). "Our results deepen our understanding of the tumor suppressor function of SPOP and provide new insights into regulation of PCa oncogene PrLZ by SPOP-mediated ubiquitination and degradation." (PMID 35194188, 2022). "The volumes of the tumours that developed from SPOP knockdown HeLa cells were smaller than those of NC group." (PMID 36042498, 2022). "From a therapeutic point of view, these results translate into a fine sensitivity of ERG-positive tumor cells to SPOP inhibition with a recently developed small molecule inhibitor." (PMID 35267426, 2022). "Our studies reveal a unique oncogenic role of stress responsive protein G3BP1 that negatively regulates tumor-suppressive SPOP ubiquitin ligase, leading to upregulation of AR signaling and prostate tumorigenesis." (PMID 34795264, 2021). "Either loss-of-function mutations of SPOP or gain-of-function mutations of PDK1 in their binding region all attenuate SPOP recognizing and ubiquitinating PDK1, leading to elevat PDK1 protein abundance, AKT kinase activity and benefit of tumor malignancies." (PMID 34353330, 2021).
tumor (continued). "In this setting, mutant SPOP (SPOP-Y87C, -F102C, -W131G, -F133S) dramatically decreased cancer cells’ proliferation in culture and the growth of xenograft tumor models in vivo." (PMID 33531470, 2021). "PCa is generally a slow proliferating tumor with few key mutations and genetic alterations commonly found in patients such as TMPRSS-ERG, SPOP, FOXA1, PTEN35,36." (PMID 33602919, 2021). "Finally, we identified 18 genes with point mutations or insertions/deletions with unknown clinical significance, including a missense mutation in the speckle-type pox virus and zinc finger protein (SPOP) gene (p.F133L) with a tumor variant allele frequency of 20.6%." (PMID 33568750, 2021). "The tumor suppressor SPOP (speckle-type POZ protein) was demonstrated to localize into liquid nucleolar bodies, and mutations in cancer-specific amino acids W131G and F33V disrupt this localization." (PMID 34884901, 2021). "Meanwhile, SPOP promotes the tumor invasiveness by degrading large tumor suppressor 1(LAST1) or enhancing the transcription factor β-catenin protein expression, as well as its nuclear translocation in WNT signaling pathway." (PMID 34021128, 2021). "Conversely, we assessed the consequence of ERG overexpression in LNCaP cells under low DHT levels where mutant SPOP triggers AR signaling and tumor growth 19,23." (PMID 33531470, 2021). "For example, some studies supported that reduced SPOP expression was commonly correlated with a lager tumor size, the present of lymph metastasis and poor differentiation." (PMID 34838022, 2021). "We first provide experimental evidence demonstrating that the E3 ubiquitin ligase SPOP plays a critical tumor suppressive role in PrCa by specifically binding and promoting the degradation of HnRNPK via polyubiquitination." (PMID 34857003, 2021). "As a ubiquitin E3 ligase, SPOP degrades different substrates in different tumors, and thus plays different roles in tumor development." (PMID 34021128, 2021). "Cullin3-SPOP polyubiquitinates and destabilizes PD-L1 and malfunction of SPOP results in a decreased number of tumor-infiltrating cells in mouse models." (PMID 33466790, 2021). "The corrections of SPOP expression with expression disparity, tumor differentiation, clinical stage and survival were analyzed." (PMID 34838022, 2021). "To assess the underlying molecular biology of the antagonistic relationship between ERG-fused and SPOP-mutants tumors, we interrogated the transcriptomes from the TCGA cohort to nominate differences across these tumor subtypes." (PMID 33531470, 2021). "SPOP, an E3 ubiquitin ligase adaptor, can function either as a tumor suppressor or a tumor promoter." (PMID 33158056, 2020). "More directly, Cullin 3SPOP has been reported to destabilize HDAC6 via polyubiquitination, and this interaction has suggested that SPOP serves a tumor suppressor function through this mechanism." (PMID 33020410, 2020). "We demonstrate that the EGFR–ERK axis accelerates tumor-promoting metabolic programs by mitigating SPOP-mediated ILF3 poly-ubiquitination and subsequent degradation." (PMID 31772275, 2020). "Nonetheless, multiple studies have shown that SPOP acts as a tumor suppressor in PCa by degrading its oncogenic substrates." (PMID 33158056, 2020). "While AURKA is a well-established oncogene, SPOP can act as a tumor-promoter or tumor-suppressor depending on the cell type." (PMID 33158056, 2020). "To further validate the results, we examined the expression of ADAMTS9‐AS2 and the relationship between ADAMTS9‐AS2 expression and the expression of SPOP in tumour tissues by using the GEPIA database." (PMID 32160650, 2020).
tumor (continued). "Taken together, these findings suggest that SPOP plays an oncogenic role in KC cells via its cytoplasmic accumulation, resulting in degradation of tumor suppressive substrates of SPOP." (PMID 31901237, 2020). "In PCa, SPOP acts as a tumor suppressor as it binds and degrades several oncogenic targets including AR." (PMID 33158056, 2020). "SPOP, an adaptor protein for E3 ubiquitin ligase can function as a tumor-suppressor or a tumor-enhancer." (PMID 33158056, 2020). "Genome-wide next generation sequencing studies have revealed that SPOP is frequently mutated in a number of cancer types such as prostate and endometrial, thus suggesting SPOP as a putative tumor suppressor." (PMID 32512734, 2020). "Mutations of SPOP and alterations in ETS transcription factor ERG are mutually exclusive in localised and metastatic tumours, representing different subtypes of tumours." (PMID 32365491, 2020). "We also assessed the underlying impact of SPOP on LNM, which possessed a crucial role in tumor recurrence and survival of cancer patients." (PMID 31577764, 2019). "Multiple studies have illustrated that SPOP exerts its tumor suppressive function through degradation of oncogenic substrates in PCa." (PMID 30237511, 2019). "SPOP is a tumor suppressor protein and substrate adaptor of the cullin 3-RING-ubiquitin ligase (CUL3); tumor-associated SPOP mutations disrupt substrate binding and ubiquitination, leading to increased expression of oncogenic substrates." (PMID 31366128, 2019). "The results showed that CYCLIN E1 increased tumor volume and SPOP expression greatly repressed it; importantly, SPOP expression reversed the effect caused by CYCLIN E1 overexpression (left)." (PMID 30237511, 2019). "The results suggest SPOP expression repressed tumor volume and weight of DU145, same as previous observation, and increased the tumor number formed by 769-P." (PMID 30237511, 2019). "Our group have recently identified SETD2 as one of SPOP substrates, which is the major histone H3K36me3 methyltransferase in mammal and a tumor-suppressor in many cancers." (PMID 30237511, 2019). "To identify molecular mediators of the tumor suppressive function of SPOP, we performed a yeast two-hybrid screen in a HeLa cDNA library using the full-length SPOP as bait." (PMID 29996942, 2018). "SPOP mediated the C/EBPα-regulated suppression of invasion, migration and proliferation in vitro and tumor growth in vivo." (PMID 30607139, 2018). "Functionally, we demonstrated that the tumor suppressor SPOP suppresses the cancer cell proliferation and migration partly through negatively regulating the stability of HDAC6." (PMID 28599312, 2017). "Further, these alterations lead to substantial heterogeneity in tumor samples and have been used to define PCa molecular subtypes based on fusion of ETS family genes (ERG, ETV, ETV4, or FLI1) and mutations in SPOP, FOXA1, or IDH1." (PMID 28750683, 2017). "To identify molecular mediators of the tumor suppressive function of SPOP, we performed a yeast two-hybrid screen in a human fetal brain cDNA library using the full length SPOP as bait." (PMID 28448495, 2017). "HDAC6 plays an important role in tumorigenesis, invasion and metastasis, whereas SPOP has been shown to be a well-characterized tumor suppressor." (PMID 28599312, 2017). "Mechanistically, SPOP controls the ubiquitination and degradation of several tumor suppressors residing in the cytoplasm, such as PTEN, ERK phosphatases, Daxx, and Gli2." (PMID 27200299, 2016). "RNA samples of 51 high and low inflammation tumor tissues of the patient cohort profiled for autoantibodies were screened via Sanger sequencing of a PCR-amplified SPOP c-DNA fragment." (PMID 26863016, 2016). "Our previous study has reported that SPOP acts as a tumor suppressor by inhibiting cell proliferation and migration in CRC." (PMID 28032859, 2016).
tumor (continued). "The data showed that the ability of resisting cell death in Lovo-shSPOP cells was enhanced compared with control cells, while overexpression of SPOP in HCT116 promoted tumor cell apoptosis." (PMID 28032859, 2016). "This cytoplasmic retention of SPOP confers tumor-promoting activities, which is opposite to the function of SPOP in the nucleus." (PMID 27200299, 2016). "While KLHL20 mainly plays a tumor-promoting role, SPOP elicits both tumor-promoting and suppressive effects depending on its subcellular localization and cell context." (PMID 27200299, 2016). "Together, our study elucidates the tumor protective function of SPOP through inhibiting Hh/Gli2 pathway, and the possible molecular mechanism of Gli2 stability regulated by SPOP." (PMID 25204354, 2014). "PCa-associated mutant versions of SPOP protein are unable to bind to SRC-3 and trigger its degradation thereby validating the tumor suppressing role of SPOP." (PMID 25277175, 2014). "Collectively, these findings suggest that SPOP may function as a tumor suppressor in PCa, in part by promoting the degradation of BRD2, BRD3, and BRD4." (PMID 40521202, 2025). "However, HCC-associated mutations or pathologically low expression of SPOP lead to aberrant stabilization of LMNB2, which in turn, directly induces PD-L1 transcription, thereby promoting tumor immune evasion of HCC." (PMID 40483310, 2025). "Consequently, SPOP inhibitors synergized with immune checkpoint blockade to suppress B16 tumor growth in syngeneic murine models and enhanced the efficacy of CAR.CD19-T cell therapy." (PMID 41148213, 2025). "Conversely, pathways associated with cell cycle progression and DNA damage repair were negatively correlated with SPOP expression, suggesting that SPOP exerts tumor-suppressive effects through mechanisms such as metabolic reprogramming and cell cycle inhibition." (PMID 40657370, 2025). "Importantly, combinatorial targeting of LMNB2 with Atezolizumab (PD-L1 inhibitor) displayed a synergistic effect on suppressing tumor progression both in vitro and in vivo, particularly in HCC models with SPOP mutations or LMNB2 overexpression." (PMID 40483310, 2025). "Invadopodia formation is characteristic of tumor metastasis, which generally manifests as colocalization of F-actin and Cortactin, and IF revealed that after SPOP was knocked down, the colocalization of Cortactin and F-actin was significantly increased, suggesting an increase in invadopodia." (PMID 41213915, 2025). "Given the dual roles of SPOP as both an oncogene and tumor suppressor in a cancer type-specific manner, the development of SPOP-targeting agents may prove crucial for the treatment of diverse cancers." (PMID 40521202, 2025). "Thus, SPOP appears to exert its tumor-suppressive function, in part, by targeting c-MYC for ubiquitination-mediated proteasomal degradation." (PMID 40521202, 2025). "In this study, in terms of function, we found that SPOP plays a tumor suppressor role in CRC." (PMID 41213915, 2025). "Investigating tumor therapy strategy in tumors with high expression of SPOP and RIPK1." (PMID 41122967, 2025). "Furthermore, functional analyses reveal that SPOP hinders the tumor-suppressive effects of LZTS2 on CRC cell proliferation and metastasis, whereas HAUSP enhances LZTS2's anti-tumor activity in CRC cells." (PMID 41436424, 2025). "Moreover, we observed mutations in genes frequently associated with PC, such as SPOP, FOXA1, and KMT2C, in the tumor organoids." (PMID 40163511, 2025). "Numerous downstream substrates of SPOP have been identified across various cancers, where they regulate carcinogenesis, metabolic reprogramming, cell death, immune evasion, therapy resistance, and tumor microenvironment (TME) remodeling." (PMID 40521202, 2025). "Collectively, these findings suggest that SPOP downregulates PD‐L1 expression in tumor tissues." (PMID 39499771, 2025).